EPHX2 (epoxide hydrolase 2)
Diseases named in the same sentence as EPHX2 in open-access papers (continued):
Sharing a sentence is not in itself a finding about the gene and the disease.
EPHX2 also shares sentences with these, for which no sentence is quoted: ischemia (24 papers); myocardial infarction (16); neurodegenerative disease (14); Cognitive impairment (13); type 2 diabetes (12); metabolic syndrome (11); pulmonary fibrosis (11); Nephropathy (10); dementia (9); non-alcoholic fatty liver disease (8); asthma (7); diabetic retinopathy (7); Parkinsonism (7); psychiatric disorder (6); retinopathy (6); cognitive decline (5); heart disease (5); Impaired glucose tolerance (5); liver cancer (5); renal fibrosis (5); subarachnoid hemorrhage (5); cerebral infarction (4); chronic obstructive pulmonary disease (4); glioblastoma (4); infection (4); injury (4); liver diseases (4); pancreatic cancer (4); type I diabetes (4); acute lung injury (3).
A further 154 diseases each share a sentence with EPHX2 in 3 papers or fewer.